CGAS (cyclic GMP-AMP synthase)
Diseases named in the same sentence as CGAS in open-access papers (continued):
Sharing a sentence is not in itself a finding about the gene and the disease.
Autoimmunity (continued). "Hence, cGAS/STING signaling regulates different immune mechanisms to maintain immune homeostasis, and its altered activity predisposes the host to different infections and diseases, such as autoimmunity, aging, and cancers." (PMID 38339107, 2024). "For example, in terms of their evolutionary aspects, inflammasomes such as ALRs and NLRs are the youngest (evolved in vertebrates) of both TLRs and cGAS, which might have evolved to take care of their overactivation to prevent exaggerated inflammation (autoinflammation and autoimmunity)." (PMID 38339107, 2024). "In addition to viral DNA, self-DNA accumulated in cytosol activates cGAS to induce autoimmunity." (PMID 36217001, 2022). "Additionally, miR-23a/b dampens cGAS-mediated innate immunity and autoimmunity by targeting cGAS." (PMID 36189363, 2022). "Therefore, the cGAS-STING pathway might be suppressed by TANK even in human SLE patients to prevent pathogenesis of autoimmunity and the development of DAH." (PMID 34819357, 2022). "Because the cGAS-STING pathway has been implicated in autoinflammatory and autoimmune conditions, we chose to investigate the role of STING in a murine mixed bone marrow (BM) chimera model of autoimmunity resembling SLE, with a prominent type I interferon signature." (PMID 34938294, 2021). "However, it is largely unknown how cGAS expression is regulated during pathogen infection and autoimmunity." (PMID 33767433, 2021). "However, caspase-mediated cleavage and inactivation of cGAS probably prevent IFN-I-mediated autoimmunity, although this may come at the expense of antiviral immunity." (PMID 34718659, 2021). "cGAS senses both exogenous and endogenous DNA within cells, labeling cGAS-STING as a pivotal anti-tumor immunity mechanism, autoimmunity, sterile inflammatory responses, and cellular senescence." (PMID 40552295, 2025). "Increasing evidence indicates that cGAS–STING signaling pathway plays a pivotal role in the pathogenesis of RA, bridging innate immune sensing with chronic inflammation and autoimmunity." (PMID 41415288, 2025). "Initially regarded as primarily mediating antiviral innate immunity, the cGAS–STING axis has more recently been recognized as a critical contributor to sterile inflammation, cellular senescence, autoimmunity, and tissue injury." (PMID 41415288, 2025). "The cGAS-STING signaling pathway has emerged as a key target for therapeutic intervention due to its role in chronic inflammation, autoimmunity, and metabolic disorders." (PMID 39669992, 2024). "cGAS-STING can regulate tumorigenesis, participate in autoimmunity and is also essential for the host defense against different kinds of pathogens." (PMID 37153576, 2023). "Mutations in the TREX1 gene result in the accumulation of cytosolic DNA and the release of damaged DNA, inducing the constitutive activation of the cGAS/STING pathway and consequently aberrant inflammation and autoimmunity." (PMID 37354378, 2023). "This is consistent with TREX1’s role as an immune inhibitor that prevents cGAS-STRING initiation, with inhibition of TREX1 stimulating IFN signaling and autoimmunity, making it a potential immunomodulatory target." (PMID 37173324, 2023). "Self-DNA sensing through cGAS-STING is involved in many processes, including autoimmunity; however, the precise mechanism linking STING gain of function to the production of autoantibodies has not yet been defined." (PMID 35603217, 2022). "Moreover, none of these modifications has been linked to cGAS-mediated autoimmunity." (PMID 33767433, 2021). "In the absence of TREX1 exonuclease activity, substrate accumulation stimulates the DNA-sensing pathway cGAS-STING, which drives IFN-signaling and autoimmunity." (PMID 33868310, 2021). "Inhibition of cGAS and STING using small molecules and anti-sense oligonucleotides have been shown to ameliorate pathology in mouse models of autoimmunity, and to limit brain injury following ischemic stroke." (PMID 33868310, 2021).
Autoimmunity (continued). "Numerous studies over the last decade have shown that the cGAS‒STING signaling pathway plays an important regulatory role in pathogen infection, malignancies, and autoimmune disorders by regulating both innate immunity and adaptive immunity." (PMID 34718659, 2021). "The mtDNA is sensed by the cGAS‐STING axis leading to sustained production of type I IFN response and autoimmunity." (PMID 32715615, 2020). "On the other hand, cytosolic DNA sensing by cGAS to activate STING incited anti-viral immunity, spontaneous autoimmunity in mice with defective DNA catabolizing enzymes and anti-tumor immunity." (PMID 32625215, 2020). "More interestingly, both RLR and cGAS-STING pathways can also be activated by RNA or DNA species from the host cells themselves, resulting in autoimmunity or enhanced immune surveillance." (PMID 30089112, 2018). "Taken together, the DNA components in CSE-NETs promoted NF-κB-, but not type-I IFNs-, dependent autoimmunity via cGAS/TLR9 in long-term CS-induced COPD." (PMID 38880789, 2024). "mtDNA interacts with and activates a wide variety of immunostimulatory DNA sensors, such as cyclic guanosine monophosphate-adenosine monophosphate synthase (cGAS) and Toll-like receptors (TLR7/9), which can induce autoimmunity, activating type I interferon inflammatory responses." (PMID 36430958, 2022). "There, mtDNA interacts with and activates a variety of immunostimulatory DNA sensors, including cyclic guanosine monophosphate-adenosine monophosphate synthase (cGAS) and Toll-like receptors (TLR7/9), which can trigger autoimmunity by activating IFN-α inflammatory responses." (PMID 36430958, 2022). "Accordingly, therapeutic avenue through targeting the cGAS-STING pathway may be realized one day for infections, autoimmunity, inflammatory diseases and cancers." (PMID 34158863, 2021). "The finding that the cytosolic DNA sensor cGAS promotes therapeutic responses and is required to induce IDO after DNP treatment reveals that cGAS senses DNP cargo DNA to activate STING/IFN-I signaling in DCs competent to express IDO and suppress autoimmunity." (PMID 32625215, 2020). "On one hand, cGAS-STING activating therapies can trigger an intended pro-inflammatory response to cancers, but it can potentially also initiate a cascade of autoimmunity and inflammation, which can be as devastating as the cancers these treatments were designed to circumvent." (PMID 32774773, 2020). "On the other hand, modulation of the cGAS-STING pathway in HSPCs may boost anti-infection or antitumor immunity and suppress autoimmunity and peripheral inflammation." (PMID 33329537, 2020). "In summary, we have discovered and characterized a small molecule that shows potent and selective inhibition of cGAS dsDNA-dependent enzymatic activity in vitro and in cells, including primary macrophages taken from a Trex1 null mouse model of AGS autoimmunity." (PMID 28963528, 2017). "CENPA expression and micronuclei formation correlate highly with activation of the cGAS-STING/IFN-β pathway as well as markers of reactive oxygen species (ROS) and fibrosis, ultimately suggesting a link between centromere alterations, chromosome instability, SSc autoimmunity, and fibrosis." (PMID 36400785, 2022). "As STING mutations related to human autoimmunity could induce constitutive ER exit and stimulate STING without cGAMP binding, the cGAS–STING pathway is pivotal for preventing massive infections and valid anti-tumor immune responses." (PMID 35397620, 2022). "Although RLRs and cGAS-STING are non-essential genes, animals and humans with mutations in RLRs, cGAS-STING, or downstream signaling components are prone to immune dysregulation, such as autoimmunity and infectious susceptibility." (PMID 34868827, 2021).
Autoimmunity (continued). "This review gives a detailed account of the interplay between the caspase family and the cGAS‒STING signaling pathway, which will shed light on developing novel therapeutics targeting the caspase family and cGAS‒STING signaling in antiviral innate immunity, cancer, inflammatory, and autoimmunity." (PMID 34718659, 2021). "Herein, we present evidence that CS-induced NETs-DNA sensed by cGAS and TLR9 in AECs and DCs promotes NF-κB-, but not type-I IFNs, dependent autoimmunity in long-term CS-induced COPD." (PMID 38880789, 2024).
colorectal cancer (63 papers, 2017 to 2026). A primary or metastatic malignant neoplasm that affects the colon or rectum. "Literature investigation revealed that HCT116 cells, as well as several other colorectal cancer lines, are reported to have deficiency in cGAS expression, and cannot activate STING." (PMID 38358346, 2024). "Another important finding in the present study was that cGAS-STING pathway–related clusters were associated with various immune cell infiltration levels in colorectal cancer." (PMID 37355491, 2023). "For example, cGAS knockout makes mice susceptible to colitis-associated colorectal cancer due to disruption of intestinal barrier integrity, decreased stem cell number, inflammation with abundant myeloid-derived suppressor cells (MDSC), and STAT3 activation." (PMID 38139802, 2023). "These strategies overcome the low antitumor immunity elicited by RT in cGAS/STING-deficient colorectal cancer." (PMID 35835756, 2022). "Taken together, this therapeutic strategy represents a novel targeted treatment option for patients with colorectal cancer, especially cGAS/STING-deficient patients." (PMID 35835756, 2022). "Interestingly, this elevation in cGAS gene expression was associated with early-stage colorectal cancer." (PMID 39050748, 2024). "Additionally, it suggested that the capability of Midostaurin (PKC412) to restrict colorectal carcinoma cell growth is associated with the activation of the cGAS-STING signaling." (PMID 37781354, 2023). "However, TRAIL-dependent cell death was attenuated in cGAS-deficient colorectal cancer cells." (PMID 35835756, 2022). "Chronic, dysregulated inflammation contributes to colitis-associated colorectal cancer (CRC), and the cGAS-STING pathway represents a central but therapeutically challenging node because both insufficient and excessive STING activity can be pathogenic." (PMID 41828473, 2026). "In colorectal cancer, patients with high cGAS-STING expression exhibit better response rates and longer survival following immune checkpoint blockade." (PMID 40830678, 2026). "Search terms included combinations of “cGAS-STING”, “colitis-associated colorectal cancer”, “IBD”, “intestinal inflammation”, “epithelial barrier”, and “tumorigenesis”." (PMID 40507791, 2025). "Radiotherapy using irinotecan (IRIN) silicasome nanoparticle sensitizes colorectal cancer to immunotherapy by modulating the cGAS/STING pathway." (PMID 39367110, 2025). "Our study unveils caspase-activated DNase (CAD) as a previously unrecognized suppressor of cGAS/STING signaling that governs radiosensitivity in colorectal cancer (CRC)." (PMID 40849416, 2025). "Here we show that mTORC2-mediated phosphorylation of human cGAS serine 37 promotes its chromatin localization in colorectal cancer cells, regulating cell growth and drug resistance independently of STING." (PMID 39080411, 2024). "Compared to controls, KGA messenger RNA levels and glutaminase activity were significantly increased in cGAS-knockdown colorectal cancer cells." (PMID 39080411, 2024). "Our previous study suggested that dMMR/MSI-H colorectal cancer (CRC) exhibited higher expression of tumor cell-intrinsic cGAS–STING, concomitant with higher infiltration of CD8+ TILs, compared to pMMR/MSS CRC21." (PMID 39242811, 2024). "Our findings suggest that lovastatin-induced apoptosis is at least partly mediated through the cGAS-STING signaling pathway by triggering mtDNA accumulation in the cytosol in human colorectal cancer HCT116 cells." (PMID 38929118, 2024). "In summary, our findings underscore the potential of the G4 ligand TMPyP4 as a dual strategy to target colorectal cancer: inhibiting cancer progression and augmenting anti-tumor immunity through the activation of cGAS-STING pathway." (PMID 39528472, 2024). "In this study, we chose colorectal cancer patients exhibiting simultaneous NF-κB overactivation and cGAS inactivation as the research model." (PMID 38782895, 2024).
colorectal cancer (continued). "Western blot analysis also revealed that cGAS was expressed at low levels in two colorectal cancer cell lines (Lanes 2–3 and Original full length western blots image 1)." (PMID 38782895, 2024). "Surprisingly, in inflammation-induced colorectal cancer, the cGAS-STING pathway can also inhibit inflammation, thereby limiting tumorigenesis." (PMID 38523155, 2024). "This work aimed to develop and validate molecular subtypes related to cGAS-STING pathways for colorectal cancer using Bulk RNA-seq and single-cell RNA-seq (scRNA-seq) data." (PMID 37355491, 2023). "The TLR3/cGAS‐STING‐IFN signaling has recently been reported to be disturbed in colorectal cancer due to deregulated expression of the genes involved." (PMID 31869529, 2020). "Hafnium oxide nanoparticles (i.e., NBTXR3) in combination with IR enhanced DNA damage in a colorectal cancer cell line leading to increased activation of the cGAS–STING pathway." (PMID 33238631, 2020). "Moreover, polymorphisms in cGAS rs72960018, cGAS rs9352000 and STING rs13153461 have been associated with increased colorectal cancer risk." (PMID 41476984, 2025). "Together, these results indicate that KGA inhibition can overcome cGAS deficiency-induced chemoresistance and that targeting both ccGAS and KGA may represent a promising therapeutic strategy for colorectal cancer." (PMID 39080411, 2024). "We have recently demonstrated that depriving colorectal cancer cells of serine results in mitochondrial dysfunction coupled with the cytosolic accumulation of mitochondrial DNA and consequent activation of CGAS- and STING-dependent tumor-targeting immune responses." (PMID 39206097, 2024). "Given that TMPyP4 increased DNA damage in colorectal cancer cells, we hypothesized that TMPyP4 might enhance the immune response through the cGAS-STING pathway." (PMID 39528472, 2024). "Currently, studies showed that cGAS-STING pathway was activated in colorectal cancer." (PMID 37355491, 2023). "In summary, we developed cGAS-STING pathway–related subtypes for colorectal cancer, which could be used to predict prognosis." (PMID 37355491, 2023). "This study identified the clustering subtypes of colorectal cancer based on the characteristics of cGAS-STING-related pathways, and correlated the characteristics of each subtype with patients’ prognosis, gene mutation, immune status, and immune cell infiltration." (PMID 37355491, 2023). "The optimal condition of cytosolic DNA and cGAS-STING pathway protein expressions in colorectal cancer lines could be further clarified for clinical therapy." (PMID 36230769, 2022). "The cyclic GMP-AMP synthase (cGAS)-stimulator of interferon genes (STING) pathway has emerged as a critical innate immune pathway that could virtually impact nearly all aspects of tumorigenesis including colorectal cancer." (PMID 37355491, 2023). "However, dysregulation of cGAS/STING constrains radiotherapy-induced antitumor immunity and type I IFN-dependent cell death and is associated with shorter survival of patients with colorectal cancer (CRC)." (PMID 35835756, 2022). "The tumor cell-intrinsic cyclic GMP–AMP synthase (cGAS)–stimulator of interferon genes (STING) pathway is critical for activating anti-tumor immunity and enhancing immune checkpoint blockade therapy in colorectal cancer (CRC)." (PMID 40451897, 2025). "This review discussed the research progress of cGAS-STING pathway mediating common digestive diseases, including inflammatory bowel disease, liver disease, colorectal cancer, gastric cancer, esophageal cancer, pancreatitis, and pancreatic cancer." (PMID 40621423, 2025). "We selected two representative human colorectal cancer cell lines, SW620 and LOVO, to detect the expression of cGAS and NF-κB p65." (PMID 38782895, 2024). "In summary, our discoveries underscore the pivotal role of PREX2 in colorectal cancer (CRC) radiation resistance, with its influence predominantly channeled through the cGAS/STING/IFN signaling pathway." (PMID 38609982, 2024).
colorectal cancer (continued). "The nuclease benzonase was included in all buffers to minimize post-lysis DNA binding by cGAS, then Co-IP validated interactions between cGAS and SWI/SNF components such as ARID1A, SMARCA4 and SMARCC2 in colorectal cancer cells." (PMID 39080411, 2024). "In this study, we were the first to study the immune heterogeneity of CGAS-STING pathway in colorectal cancer, and we divided colorectal cancer samples into two subtypes with significant characteristic differences." (PMID 37355491, 2023). "Future studies should be performed to investigate the detailed mechanism between cGAS-STING pathway members and colorectal cancer." (PMID 37355491, 2023). "Another study revealed that STING can regulate the cell cycle in a cGAS-independent manner in certain tumor models, such as HCT116 colorectal carcinoma." (PMID 37354378, 2023). "Recent studies have shown frequent defects in cGAS/STING-dependent signaling pathways mediated by epigenetic control in several malignancies, including lung cancer and colorectal cancer." (PMID 35835756, 2022). "In conclusion, the inexpensive clinical drug ciprofloxacin, a fluoroquinolone-class antibiotic, may activate the cGAS-STING signaling pathway and enhance the anti-PD1 therapeutic effects in colorectal cancer." (PMID 40643531, 2025). "The cGAS/STING pathway plays numerous roles in gut immunity, ranging from induction of antiviral immunity upon microbiota activation, to contradictory roles in colorectal cancer (CRC) and bowel diseases." (PMID 40964309, 2025). "The ability to generate cGAMP as measured by cGas expression was not significantly different between breast and colorectal cancer cell lines but was significantly lower than in lung carcinoma cell lines." (PMID 39622844, 2024). "However, other studies revealed that cGAS-STING pathway promoted tumor development and progression in Lewis lung carcinoma, brain and colorectal cancer." (PMID 38510490, 2024). "Secondly, we did not analyze the potential mechanisms of cGAS-STING pathway members in colorectal cancer." (PMID 37355491, 2023). "This indicated that cGAS-STING pathway–related clusters may be a new and effective classification system for clinical colorectal cancer patients and can reflect the immune status." (PMID 37355491, 2023). "Increasing evidence indicates that dysfunctions within the cGAS-STING signaling potentially mediate the pathogenesis of diverse digestive diseases, such as inflammatory bowel disease (IBD), non-alcoholic fatty liver disease (NAFLD), and colorectal cancer (CRC)." (PMID 40621423, 2025). "It has not been studied, however, whether cGAS-STING activation is involved in the apoptosis induced by statin treatment in human colorectal cancer cells." (PMID 38929118, 2024). "The cyclic GMP-AMP synthase (cGAS)-stimulator of interferon genes (STING) pathway plays a crucial role in activating immune cells in the tumor microenvironment, thereby contributing to a more favorable response to immune checkpoint inhibitors (ICI) in colorectal cancer (CRC)." (PMID 37345163, 2023). "The findings of the present study demonstrate and discuss the DNA sensor cGAS and cyclic GMP–AMP receptor stimulator of interferon genes (STING) as potential new targets for novel therapeutic approaches based on immune checkpoint inhibitors in microsatellite unstable stage IV colorectal cancer." (PMID 36612217, 2022). "For instance, lacking of cGAS and/or STING has been found in more than a third of colorectal cancers." (PMID 32174922, 2020).